KIF11 (kinesin family member 11)
Diseases named in the same sentence as KIF11 in open-access papers (continued):
Sharing a sentence is not in itself a finding about the gene and the disease.
cancer (156 papers, 2006 to 2026). A tumor composed of atypical neoplastic, often pleomorphic cells that invade other tissues. "KIF11 is expressed more frequently in a variety of cancers and is associated with a bad prognosis for cancer, according to recent studies." (PMID 39911278, 2025). "The consistent association across multiple cancer types underscores the potential of KIF11 and KIF14 as prognostic biomarkers and highlights the importance of further investigating their roles in tumor progression and patient outcomes." (PMID 40075652, 2025). "Multiple research studies have consistently demonstrated a significant association between the expression of KIF11 and prognosis in different types of cancer." (PMID 41462522, 2025). "Meanwhile, immune cells interact with normal cells to impact the metabolism in the TME, promoting cancer and lipid metabolism involving KIF11, causing PDAC progression." (PMID 38672404, 2024). "We identified several proteins with high interaction scores (Cna2, Kif20a, Kif11, Cdk1, and Cdc20) that are closely associated with various cancers." (PMID 39596644, 2024). "Comparative study revealed that KIF11 was a powerful biomarker and associated with immune, targeted, and chemotherapeutic outcomes in various cancers." (PMID 36742345, 2022). "Detailed information about KIF11 mutations in different human cancer types indicated that the mutation sites of KIF11 distributed in the whole gene body including the KISc and microtubule binding domains." (PMID 36742345, 2022). "Subsequently, the association between KIF11 expression and immune checkpoint genes in human cancers was explored." (PMID 36742345, 2022). "Collectively, these results indicated that KIF11 expression was strongly related to cancer stemness, and epigenetic methylation of KIF11 in patients was associated with prognosis across various human cancers." (PMID 36742345, 2022). "Knockdown of KIF11 or use of specific inhibitors of KIF11 can activate the response of the spindle checkpoint, causing mitotic stress and finally leading to programmed cell death in cancer cells." (PMID 33995648, 2021). "KIF11 has been shown to be overexpressed in a broad range of cancer what contributes to tumorigenesis, being associated with a worse prognostic." (PMID 34548908, 2021). "KIF11 expression was found to be altered and associated with patient survival in numerous types of human cancer, which suggests its contribution to cancer development and progression." (PMID 34575892, 2021). "Kinesin family member 11 (KIF11) has been reported to affect the progression of several cancers, and its high expression associates with the prognosis of patients." (PMID 33490265, 2021). "Through the cancer genome atlas (TCGA) database and immunohistochemical (IHC) staining of patients' specimens, we determined that KIF11 was highly expressed in HCC tissues and associated with prognosis." (PMID 33490265, 2021). "We observed significant reduction in the mRNA levels of Kif11, Aurka, Cyclin D1 (Ccnd1), and Cancer susceptibility candidate 5 (Casc5) in Id KD compared to the controls." (PMID 32911668, 2020). "However, while kinesins have been implicated in cancer progression, further studies are required to elucidate the precise molecular mechanisms underlying KIF11 and KIF14 expression in EC." (PMID 40075652, 2025). "Hence, these studies provide insights into the involvement of KIF11 in tumor cell metabolism, which is another essential hallmark of cancer that changes the microenvironment for progression." (PMID 38672404, 2024). "High KIF11 expression was associated with poorer prognosis in most human cancer types except THYM." (PMID 36742345, 2022). "Recent experimental research has suggested that the aberrant expression of KIF11 (either upregulation or silencing), may be a pathogenic event contributing to cancer development and/or progression through genomic instability." (PMID 34575892, 2021).
cancer (continued). "Also, KIF11 is overexpressed in several cancers and is associated with poor prognosis in HCC." (PMID 40546347, 2025). "Meanwhile, KIF11 was associated with drug sensitivity and could serve as a powerful biomarker for predicting immune, targeted, and chemotherapeutic outcomes in different cancers." (PMID 36742345, 2022). "Together, these findings support a model in which Src-mediated phosphorylation at Y211 acts as a rheostat to tune KIF11 mechanochemistry and spindle assembly dynamics, linking cancer-relevant kinase signaling to mitotic force generation." (PMID 41648279, 2026). "In docetaxel-resistant TNBC cells, KIF11 knockdown inhibited the proliferation of CD44+/CD24-cancer stem-like cells and removed their self-renewal capacity." (PMID 41487287, 2025). "KIF11 has been shown to activate the Wnt/β-catenin and mevalonate metabolism pathways, driving cancer cell proliferation." (PMID 40075652, 2025). "KIF11 is overexpressed or amplified in many cancers and correlates with poor prognosis and resistance to microtubule‐targeting agents." (PMID 41439111, 2025). "The human KSP gene, KIF11, is located at q23.33 on chromosome 10; however its transcriptional regulation has only been described in cancer cells." (PMID 41009541, 2025). "The genomic instability brought on by KIF11 abnormalities promotes the spread of cancer, for instance, by accelerating invasion and metastasis." (PMID 39911278, 2025). "Based on its indispensable contributions to accurate chromosome segregation, numerous studies have elucidated the crucial involvement of KIF11 in cancer development." (PMID 38672404, 2024). "In pancreatic adenocarcinoma, the downregulation of parkin stimulates the formation of spindle multipolarity, cancer cell proliferation, and tumorigenic properties by elevating the KIF11 expression level." (PMID 38672404, 2024). "MicroRNA (miRNA) influences protein synthesis via the post-transcriptional regulation of messenger RNA (mRNA), which has been demonstrated to regulate KIF11 expression in cancers." (PMID 38672404, 2024). "Aberrant upregulated KIF11 in most cancer types has been demonstrated via pan-cancer analysis and immunohistochemistry-based analyses, as well as in vitro experiments, contributing to tumorigenesis and progression." (PMID 38672404, 2024). "Then, we summarize the clinical significance and regulation of KIF11 expression, present the oncogenic functions of KIF11 in different hallmarks of cancers, and, finally, summarize the research on KIF11 inhibitors and offer future research directions." (PMID 38672404, 2024). "On the contrary, KIF11 is usually expressed at high levels in cancer cell lines and promotes tumor occurrence and progression." (PMID 38464517, 2024). "Considering that KIF11 knockdown has a strong effect on cell growth, we then employed KIF11 inhibitors commonly used in cancer research." (PMID 39113697, 2024). "Since the involvement of ASPM in the Wnt signaling pathway has been reported in several cancers, the mediation of KIF11 throughout this mechanism should be explored in different cancers to give insights for targeted drug development." (PMID 38672404, 2024). "Various types of KIF11 post-translational regulation are essential in both normal cells and oncogenic functions in cancer cells, including phosphorylation, acetylation, and ubiquitination." (PMID 38672404, 2024). "With an accumulating number of studies reporting the dysregulation mechanisms of KIF11 in cancers, significant investigations have been conducted to elucidate the oncogenic properties of this kinesin." (PMID 38672404, 2024). "Various oncogenic signaling pathways and several protein partners are driven by KIF11, promoting important hallmarks of cancers, including cancer cell proliferation, invasion, and metastasis." (PMID 38672404, 2024).
cancer (continued). "Although the expression of KIFC1 did not significantly differ between MP and BP cell lines, KIFC1 can serve as a target to promote KIF11/KIF15-dependent centrosome declustering in BP cancer cells." (PMID 39074902, 2024). "When combined with other investigations exploring the relationship between aberrant KIF11 expression and immune cell infiltration, these studies offer valuable insights into the roles of KIF11 in the cancer microenvironment." (PMID 38672404, 2024). "In relation to cancer, KIF11 has been found to support cancer proliferation via the Wnt/β-catenin pathway." (PMID 38672404, 2024). "KIF11-mediated angiogenesis has been identified in several cancers and occurs mainly through KIF11 interacting with the vascular endothelial growth factor (VEGF), an angiogenic inducer that participates in solid tumors growth." (PMID 38672404, 2024). "Recently, an increasing quantity of data have demonstrated the upregulated expression of KIF11 in various cancers, promoting the emergence and progression of cancers." (PMID 38672404, 2024). "KIF11 promotes cancer proliferation, invasion, and metastasis mainly through regulating the cell signaling pathways." (PMID 38672404, 2024). "As a gene target, KIF11 was chosen because it is an essential gene for mitosis that is overexpressed in some cancers, making it a promising target for cancer treatment." (PMID 37241945, 2023). "KIF11 has also been identified by the pharmaceutical industry as a viable target to develop anti-cancer drugs." (PMID 37894278, 2023). "Although these KIF11 inhibitors are generally well tolerated by patients, the clinical response rates as monotherapies in adult patients with advanced cancers are typically less than 10%." (PMID 37894278, 2023). "At the same time, paired PDAC tissues and normal pancreatic tissues from 3 patients were collected and qPCR detection showed that KIF11 expression in cancer tissues was significantly higher than that in normal tissues." (PMID 38012214, 2023). "Given that there are several KIF11 inhibitors that have been tested in clinical trials for different types of cancers, we tested the three most widely used inhibitors, e.g., ispinesib, filanesib, and SB-743921 (also known as kinesin spindle protein inhibitor)." (PMID 37894278, 2023). "In the present study, we conducted a comprehensive analysis of the KIF11 gene based on multiomics data and investigated the roles of KIF11 in oncogenesis, progression, tumor immune infiltration, and therapy outcome from the perspective of pan-cancer." (PMID 36742345, 2022). "In the present study, we conducted a comprehensive analysis of the KIF11 gene based on multiomics data to investigate the roles of KIF11 in oncogenesis, progression, and therapy from the perspective of pan-cancer." (PMID 36742345, 2022). "Our results indicated that genomic alteration of KIF11 occurred in 1.5% of patients with various cancer types." (PMID 36742345, 2022). "KIF11 expression was significantly upregulated in tumors and showed strong relationships with pathological stage and prognosis across different cancer types." (PMID 36742345, 2022). "All the results above indicated that KIF11 expression was closely related to the prognosis of various cancer types." (PMID 36742345, 2022). "The results of the UALCAN database showed that KIF11 expression was significantly higher among most cancer types, which was consistent with the TIMER and GEPIA database results." (PMID 36742345, 2022). "Coexpression analysis revealed that KIF11, KIF18B, KIF23, and MKI67 were positively associated with the expression of IQGAP3 in all cancer types presented in the heatmap." (PMID 36164370, 2022). "To better understand the prognostic value and potential mechanism of KIF11 expression in pan-cancer, we comprehensively analyzed the prognostic value of KIF11 in human cancers by Cox proportional hazards model." (PMID 36742345, 2022).
cancer (continued). "Most studies use KIF11 overexpression only as a prognostic marker in cancer, correlating with poor patient survival." (PMID 35929456, 2022). "This study would provide insights into the role of KIF11 in cancer initiation, progression, and tumor immunotherapy from the perspective of pan-cancer, but some limitations still exist." (PMID 36742345, 2022). "And the results indicated that KIF11 expressed differently in different immune and molecular subtypes of various cancer types." (PMID 36742345, 2022). "Our pan-cancer analysis provides a comprehensive understanding of the functions of KIF11 in oncogenesis, progression, and therapy in different cancers." (PMID 36742345, 2022). "Further in-depth analysis characterized CCNA2/MKI67/KIF11:miR-30a-5p:VPS9D1-AS1 axis-related cell cycle as a prognostic biomarker, and all of these RNAs were cancer-associated crucial genes." (PMID 35186743, 2022). "Involved genes (CCNA2, MKI67, and KIF11) were found with abundant expression levels in many tissues, and they showed a significantly upregulated expression pattern in many cancer types." (PMID 35186743, 2022). "Inhibitors of the mitotic kinesin Kif11, such as ispinesib, have been ineffective anti-cancer therapies because of the development of resistance." (PMID 35732128, 2022). "We explored genetic alterations of KIF11 using cBioPortal, and the results indicated that genomic alteration of KIF11 occurred in 1.5% of patients across various cancer types." (PMID 36742345, 2022). "Emerging evidence revealed that KIF11 plays pivotal roles in cancer initiation, development, and progression." (PMID 36742345, 2022). "In recent years, numerous studies have shown that KIF11 participates in the growth and development of a variety of human cancers." (PMID 36742345, 2022). "Because high levels of the KIF11 expression indicate robust cell proliferation, anti-KIF11 therapy is emerging as a promising cancer therapy approach." (PMID 35669725, 2022). "In contrast, KIF11 protein expressed at a high level in almost all cancer cell lines, which was consistent with the HPA, GTEx, and CCLE database results." (PMID 36742345, 2022). "The results from the MethSurv database indicated that the methylation status of single CpG island in KIF11 promoter was correlated with survival probability in different cancer types." (PMID 36742345, 2022). "It was found that KIF11 is profoundly upregulated in many kinds of cancers such as glioblastoma and brain tumors." (PMID 35251692, 2022). "For further identification of the prognostic significance of KIF11 gene, the Kaplan-Meier survival curve of human cancers with high or low KIF11 expression was analyzed by the GEPIA database." (PMID 36742345, 2022). "Our results showed that KIF11 was a powerful cancer immune evasion biomarker compared with standardized biomarkers in immune checkpoint blockade subcohorts." (PMID 36742345, 2022). "The results from the GTEx and CCLE database also proved that KIF11 mRNA expression level was low among most normal tissues except bone marrow and testis but high in almost all cancer cell lines." (PMID 36742345, 2022). "Our results indicated that KIF11 expression correlated positively with cancer stemness in almost all human cancer types except THYM." (PMID 36742345, 2022). "Among kinesins, KIF11 was found to enhance the stemness of cancer cells by promoting the expression of stemness transcription factors (NANOG and OCT4), leading to cell proliferation and resistance to chemotherapeutic agents." (PMID 36355541, 2022). "To better understand the function of KIF11 in cancer, we constructed the gene-gene interaction network for KIF11 by using GeneMania." (PMID 36742345, 2022). "Other KIF11 inhibitors that have shown promise in cancer therapy include curcumin and various tetrahydro-β-carboline-acetonide hybrids and thione derivatives." (PMID 36355541, 2022).
cancer (continued). "Literature confirms the importance of the top-ranked genes as KPNA2, recently identified as involved in cancer progression in several studies, or KIF11." (PMID 36175974, 2022). "The methylation level of KIF11 decreased in most cancers and was correlated with the survival probability in different human cancers." (PMID 36742345, 2022). "In other types of cancers, KIF11 also acts as an oncogene, and knockdown of KIF11 inhibits tumor growth." (PMID 33490265, 2021). "Gain-of-function and loss-of-function assay demonstrated that KIF11 regulated GBC cell cycle and cancer cell proliferation in vitro." (PMID 33613109, 2021). "KIF11 expression on actively dividing tumor cells, presented KIF11 as an attractive target for anti-cancer drugs." (PMID 34079014, 2021). "The genetic instability due to KIF11 defects leads to cancer progression, for example by increasing the development of invasion and metastasis." (PMID 33490265, 2021). "Considering the already mentioned correlation between high levels of KIF11 and worse prognostic in different cancer types, several inhibitors for this motor protein are currently being studied in clinical trials." (PMID 34548908, 2021). "The latest research suggested that KIF11 also exerts an essential regulatory effect on cancer progression." (PMID 35140744, 2021). "The gain-of-function and loss-of-function approaches were applied to demonstrate that KIF11 promotes cancer cells proliferation in vitro." (PMID 33613109, 2021). "In a previous work of our research group, we evaluated the role of several KIF11 inhibitors on cancer stem cell (CSC) population in MDA-MB-231 cells throughout the analysis of CD44 and CD24 expression." (PMID 34548908, 2021). "The colony formation assays were performed to detect cell proliferation with normal cancer cells and KIF11 depletion cells, suggesting that KIF11 depletion suppressed cell colony formation in Hep3B and SNU-475 cell lines." (PMID 33490265, 2021). "Akin to what we identified in GBM cancer stem cells, we found that KIF11 was also localized near the basal body of primary cilia in RPE1 cells." (PMID 32811879, 2020). "We identified that in the GBM cancer stem cell subpopulation, KIF11 is highly overexpressed throughout the cell cycle due to attenuated protein degradation." (PMID 32811879, 2020). "Among the top genes found by the PMN, ASXL2, BUB1B, KIF11 and TPX2 have been clinically proven to be associated with multi-cancers, which are a variety of genes commonly identified as mutated in cancers." (PMID 31888692, 2019). "Overexpression of KIF11 or TRAF4 eliminated the suppression of carcinoma cell migration by DR6 knockdown." (PMID 30186750, 2018). "The critical role of KIF11 in mitotic progression as well as in cell motility makes it an attractive candidate for developing targeted therapy in cancer." (PMID 29190901, 2017). "The kinesin spindle protein Eg5 (also known as KSP or KIF11) is an important drug target in antimitotic cancer therapy." (PMID 28489567, 2017). "An example for a mitotic kinesin that is already investigated in phase I and II clinical trials as a cancer target is the kinesin Eg5 (also called KIF11 or KSP)." (PMID 28061449, 2017). "KIF11 (kinesin family member 11), overexpressed in many cancer cells, is a molecular motor protein that plays essential role in mitosis." (PMID 29190901, 2017). "The observed invasiveness was not seen in the cells that expressed the KIF5A tail (806–1032), suggesting the importance of endogenous communication of ZBP1 and KIF11 in the invasiveness of cancer cells." (PMID 25588836, 2015). "Multiple kinesins are involved in the development of cancer, including KIF11 and KIF4A, which were down-regulated by both FAK inhibitors." (PMID 25277206, 2014). "Small molecule inhibitors of the mitotic kinesin KiF11/Eg5 are a promising new class of anti-neoplastic agents currently evaluated in clinical cancer trials for solid tumors and hematological malignancies." (PMID 24327603, 2013).